ROS1 (ROS proto-oncogene 1, receptor tyrosine kinase)
Diseases named in the same sentence as ROS1 in open-access papers (continued):
Sharing a sentence is not in itself a finding about the gene and the disease.
non-small cell lung carcinoma (continued). "It is an FDA-approved drug for the treatment of patients with metastatic non-small-cell lung cancer (NSCLC) whose tumors are ALK-positive or ROS1-positive." (PMID 35743016, 2022). "The discovery of oncogenic genes, such as epidermal growth factor receptor (EGFR), anaplastic lymphoma kinase (ALK), and ROS1, has changed the therapeutic approach for selected non-small cell lung cancer (NSCLC)." (PMID 35614407, 2022). "ROS1 fusions are identified in several tumor types and are relatively common in non-small cell lung cancer (NSCLC), spitzoid neoplasms and inflammatory myofibroblastic tumors." (PMID 35169893, 2022). "In mice bearing wild-type or ALK/ROS1-mutant non-small-cell lung cancer (NSCLC), APG-2449 demonstrates potent antitumor activity, with correlations between pharmacokinetics and pharmacodynamics in vivo." (PMID 35820889, 2022). "ROS1-rearrangements have been identified as an oncogenic driver in a variety of human solid tumors and is present in 1–2% of cases of non-small cell lung cancer (NSCLC)." (PMID 35323360, 2022). "It is licensed by the FDA for the treatment of ROS-1-positive metastatic non-small cell lung cancer (NSCLC)." (PMID 35630066, 2022). "Over the past few years, inhibitors of the c-Ros oncogene 1 (ROS1) have been approved and are currently used in clinical practice in patients with advanced non-small cell lung cancer." (PMID 35865478, 2022). "It is currently FDA-approved for treating metastatic non-small cell lung cancer with ALK or ROS-1 positivity per an FDA-approved test, ALK-positive anaplastic large cell lymphoma, and ALK-positive inflammatory myofibroblastic tumors." (PMID 36172151, 2022). "Data from 3 commercial vendors showed that the prevalence of ALK and ROS1 rearrangements in histologies other than non-small cell lung cancer and lymphoma was rare (0.1% and 0.4% respectively)." (PMID 35233056, 2022). "In case 1, the EZR-ROS1 positive lung adenocarcinoma patient who had multiple site metastases responded to crizotinib, an ROS1 inhibitor approved for ROS1-positive non-small cell lung cancer." (PMID 36167530, 2022). "The oncogenic driver mutations identified in non-small-cell lung cancer (NSCLC) include ALK gene rearrangements, ROS1 gene rearrangements, EGFR mutations, MET mutations and RET rearrangements." (PMID 35408658, 2022). "ROS-1 rearrangement is found in 0.9–2.6% of non-small-cell lung cancers (NSCLCs), mostly lung adenocarcinomas, with a significantly higher rate of women, non-smokers, and a tendency to a younger age." (PMID 35200557, 2022). "In this study, the safety, antitumor activity, and pharmacokinetics of WX-0593 were evaluated in advanced non-small cell lung cancer (NSCLC) patients with ALK or ROS1 rearrangement." (PMID 35087031, 2022). "Anaplastic lymphoma kinase (ALK) and ROS oncogene 1 (ROS1) gene fusions are well-established key players in non-small cell lung cancer (NSCLC)." (PMID 36057739, 2022). "ROS1 rearrangement, identified in ~2% of non-small cell lung cancer (NSCLC), has defined a distinctive molecular subtype." (PMID 34616749, 2021). "Entrectinib, which inhibits ROS1, ALK, three TRKs, and TRK-fusion tyrosine kinases, has shown an RR of 57% (31 of 54 patients), and is approved by the FDA for NTRK gene fusion-positive solid tumors and ROS1-positive non-small cell lung cancer." (PMID 34202544, 2021). "Riding the wave of successes of ALK and ROS1 targeted therapy in non-small cell lung cancer (NSCLC), few clinical trials are testing these treatments in ALK and ROS1 positive BTCs population." (PMID 36045702, 2021). "Crizotinib showed significant antitumor effect in patients with advanced ROS1-rearranged non-small cell lung cancers (NSCLC)." (PMID 34405544, 2021). "Chromosomal rearrangements involving ROS proto-oncogene 1 (ROS1) and the anaplastic lymphoma kinase (ALK) gene have been associated with many types of malignancies, including non-small cell lung cancer (NSCLC)." (PMID 34834176, 2021).
non-small cell lung carcinoma (continued). "In this review, we discuss the molecular epidemiology of the main druggable genetic alterations in non-small cell lung cancer, namely EGFR, KRAS, BRAF, MET, and HER2 mutations or amplification, as well as ALK and ROS1 fusions." (PMID 33435440, 2021). "Non-small-cell lung carcinomas with ALK or ROS1 fusions are sensitive to treatment with crizotinib and other, second- and third-generation inhibitors." (PMID 33441414, 2021). "Crizotinib, an analog of TQ-B3101M has been approved worldwide for the treatment of non-small-cell lung cancers (NSCLC) with rearrangements involving ALK or ROS1-positive in adults." (PMID 35115931, 2021). "Entrectinib is an FDA-approved drug for the treatment of solid tumors with NTRK fusion proteins and for ROS1-positive non-small cell lung cancers." (PMID 34948390, 2021). "Genomic rearrangements involving ROS proto-oncogene-1 (ROS1) are actionable targets in the treatment of non-small-cell lung cancer (NSCLC)." (PMID 34511132, 2021). "ROS1 gene rearrangements occur in 1–2% of human non-small cell lung cancers and confer a distinct clinical phenotype." (PMID 35295134, 2021). "For example, non-small cell lung cancer (NSCLC) regimens are organized by EGFR, ALK, BRAF, and ROS1 mutation status; kinase inhibitors are categorized by their target kinase(s) and biomarker-specific FDA labeling is noted." (PMID 32117976, 2020). "Now, a number of biomarkers in non-small-cell lung cancer (NSCLC) are being tested in routine diagnostics, including EGFR and BRAF mutations, as well as ALK and ROS1 rearrangements and PD-L1 expression." (PMID 32575424, 2020). "There are at present multiple small molecule agents/drugs that have been developed to inhibit c-MET, including crizotinib (XALKORI®) that is FDA approved for the treatment of ALK or ROS1 mutant expressing non-small cell lung cancer." (PMID 32983965, 2020). "The gene fusion of SLC34A2 and ROS1 played an important role in the progression of non-small cell lung cancer." (PMID 32429941, 2020). "These genes are frequently mutated in non-small cell lung cancer (NSCLC) with variable frequencies: EGFR, ALK; ROS1 and RET." (PMID 32928143, 2020). "Entrectinib (RozlytrekTM), which contains the indazole moiety, is also a tyrosine kinase inhibitor for the treatment of ROS1-positive non-small cell lung cancer and NTRK fusion-positive solid tumors." (PMID 32050446, 2020). "Entrectinib, an FDA approved drug for the treatment of ROS1-positive metastatic non-small cell lung cancer and NTRK gene fusion positive solid tumors, has been identified in this study as an inhibitor of DENV, hNV, and HCV." (PMID 32670253, 2020). "The drug resistance of first-line crizotinib therapy for ROS proto-oncogene 1, receptor tyrosine kinase (ROS1) fusion non-small cell lung cancer (NSCLC) is inevitable." (PMID 33324391, 2020). "Crizotinib is an effective multi-target kinase inhibitor, approved against anaplastic lymphoma kinase (ALK)- or ROS proto-oncogene 1 (ROS-1)-positive non-small cell lung carcinoma (NSCLC); however, its application is accompanied by serious side effects." (PMID 31717403, 2019). "The ROS proto-oncogene 1, receptor tyrosine kinase (ROS1) gene is proved to be a valuable therapeutic target in patients with non-small cell lung cancer (NSCLC)." (PMID 31382924, 2019). "Crizotinib, a first-generation anaplastic lymphoma kinase (ALK) inhibitor, and ceritinib and alectinib, the second-generation ALK inhibitors, have been used as the first-line treatment for non-small-cell lung cancer (NSCLC) carrying ALK or ROS1 rearrangements." (PMID 30949374, 2019). "The treatment of ROS1-rearranged non-small cell lung cancer with the TKI crizotinib is limited due to the emergence of resistance." (PMID 31399568, 2019). "Crizotinib is a multi-target inhibitor approved for the treatment of advanced non-small-cell lung cancer patients with a ROS1 rearrangement." (PMID 30029601, 2018).
non-small cell lung carcinoma (continued). "The interpretation of FISH signals followed the same criteria used for ALK and ROS1 rearrangements in non small cell lung cancers." (PMID 29515761, 2018). "Anaplastic lymphoma kinase (ALK) inhibitors are the mainstay treatment for patients with non-small cell lung carcinoma (NSCLC) harboring a rearrangement of the ALK gene or the ROS1 oncogenes." (PMID 29774128, 2018). "Crizotinib is a multi-target inhibitor, which was granted a full approval by the Food and Drug Administration (FDA) for the treatment of advanced non-small-cell lung cancer (NSCLC) patients with a ROS1 rearrangement in March 2016." (PMID 30029601, 2018). "ROS1 rearrangement was discovered in glioblastoma, non-small-cell lung cancer, cholangiocarcinoma and also recently in GC." (PMID 28683819, 2017). "Lorlatinib—a ROS1/ALK inhibitor—is currently undergoing clinical trials for the treatment of non-small cell lung cancers." (PMID 28594000, 2017). "The ROS1-rearranged non-small-cell lung carcinomas (NSCLCs) have been reported to be sensitive to the kinase inhibitor crizotinib." (PMID 27708233, 2016). "Currently, there are ongoing clinical trials of drugs targeting ROS1 for non-small cell lung cancer patients with ROS1 rearrangement." (PMID 26366867, 2015). "ROS1 rearrangement can be used as a predictive marker for response to crizotinib, a tyrosine kinase inhibitor, in patients with advanced non-small cell lung cancer (NSCLC)." (PMID 26507842, 2015). "We confirmed the expressions of ALK, MET, and ROS1 mRNA (receptor tyrosine kinases that serve as therapeutic targets in non-small-cell lung cancers), in the mouse retina." (PMID 26271036, 2015). "Currently there are no reports of the use of immunohistochemistry (IHC) in the detection of ROS1 rearrangements in order to guide treatment of advanced non-small cell lung cancer (NSCLC)." (PMID 25364439, 2014). "The understanding of the role of gene mutations (EGFR, K-RAS and MET), gene fusions (ALK) and rearrangements (ROS-1), has improved the management of non-small-cell lung cancer patients." (PMID 25149536, 2014). "Furthermore, membrane HER3 was upregulated by tyrosine kinase inhibitor treatment in non-small-cell lung cancer cell lines harboring specific driver mutations, including EGFR-activating mutations, ROS1 fusions, and ALK fusions." (PMID 41752065, 2026). "Additionally, entrectinib inhibits ROS1 and ALK, making it beneficial for metastatic, ROS1-positive non-small-cell lung cancer (NSCLC)." (PMID 40141188, 2025). "In August 2019, entrectinib received FDA approval for adult and pediatric patients ≥12 years with NTRK fusion-positive solid tumors and for ROS1-positive non-small cell lung cancer, representing a milestone in the adoption of molecularly guided cancer therapies." (PMID 41397922, 2025). "ROS1 is a type of rearrangement that is found in non-small cell lung cancer." (PMID 40584293, 2025). "Tyrosine kinase inhibitors (TKIs) targeting ROS1 fusions (ROS1+) are currently approved and recommended as the preferred first-line options in clinical guidelines for treating ROS1+ locally advanced or metastatic non-small-cell lung cancer (aNSCLC)." (PMID 40075596, 2025). "In addition to its tissue-agnostic indication, repotrectinib is also approved in patients with locally advanced or metastatic ROS1-positive non-small-cell lung cancer." (PMID 39410015, 2024). "Crizotinib, a tyrosine kinase inhibitor (TKI) targeting ALK, MET and ROS1, was approved as the first-line drug for ALK-rearranged metastatic non-small cell lung cancer, as ALK rearrangement is known as “diamond mutation” and lead to high sensitivity to ALK TKIs." (PMID 37733896, 2024). "In addition, entrectinib was also approved for the treatment of ROS1-positive non-small-cell lung cancer." (PMID 39410015, 2024).
non-small cell lung carcinoma (continued). "Crizotinib, a small-molecule tyrosine kinase inhibitor targeting ALK, MET and ROS1, is the first-line drug for ALK-positive metastatic non-small cell lung cancer and is associated with severe, sometimes fatal, cases of cardiac failure, which increases the risk of mortality." (PMID 37733896, 2024). "ROS1 rearrangements are considered rare in non-small-cell lung cancer (NSCLC)." (PMID 39195309, 2024). "Crizotinib is approved for ALK and ROS1 gene rearrangement in non-small-cell lung cancer (NSCLC)." (PMID 37046637, 2023). "Crizotinib and entrectinib are being compared head-to-head in patients with ROS1-positive non small cell lung cancer, including those who have brain metastases, in a phase III randomized controlled trial (NCT04603807) that has been accepting patients since 2021." (PMID 37511255, 2023). "Dysgeusia is also a common toxicity reported with crizotinib, a multitargeted TKI of anaplastic lymphoma kinase (ALK), mesenchymal-to-epithelial transition (MET) protein, and ROS proto-oncogene 1 (ROS1) used for the treatment of ALK-positive non-small cell lung cancer (NSCLC)." (PMID 37175898, 2023). "Depending on the type of cancer, certain biomarker tests are needed in order to decide on a treatment strategy (e.g., RAS/BRAF testing for colorectal cancer; an HER2 testing for gastric cancer; and EGFR, ALK, ROS1, and PD-L1 expression testing for non-small-cell lung cancer)." (PMID 37599324, 2023). "ROS1 rearrangement is found in 0.9%–2.6% of people with non-small-cell lung cancers (NSCLCs)." (PMID 38187090, 2023). "NGS has the potential to improve the detection of ALK and ROS1 rearrangements in cytological samples, and may become the gold standard for molecular genotyping of patients with advanced non-small cell lung cancer." (PMID 36142468, 2022). "In the last few decades, several types of genetic mutations have been observed in non-small cell lung cancer (NSCLC), including genomic alterations in anaplastic lymphoma kinase (ALK), epidermal growth factor receptor (EGFR), ROS proto-oncogene 1 (ROS1) and rat sarcoma viral oncogene homolog (RAS)." (PMID 35517800, 2022). "Some ODs have been first approved for diseases with prefixes such as “relapsed,” “refractory,” or “gene-positive” in the target disease name (e.g., “relapsed or refractory multiple myeloma” and “ROS1 fusion gene-positive unresectable advanced or relapsed non-small-cell lung cancer”)." (PMID 35906686, 2022). "Examples include EGFR, ALK, ROS1 and RET alterations in non-small cell lung cancer, rendering tumors susceptible to tyrosine kinase inhibitors, or high microsatellite instability/deficient mismatch repair (MSI-H/dMMR) in gastrointestinal tumors, which is associated with response to PD1 inhibition." (PMID 36687417, 2022). "Also, ERK mediates PD-L1 expression in NSCLC (non small cell lung carcinoma) cells with ROS1 fusion: Liu and coworker showed that both ERK phosphorylation and PD-L1 expression were down-regulated after treating HCC78 cells with PD0325901 or U0126." (PMID 34185141, 2021). "SA-PRO populations comprised patients with NTRK fusion-positive solid tumours (N = 88) or ROS1 fusion-positive non-small-cell lung cancer (N = 180) who received one or more doses of entrectinib, completed PRO questionnaires on cycle 1 day 1 and answered one or more questions on-study." (PMID 33930659, 2021). "Here we investigated the therapeutic potential of crizotinib, a TKI approved for targeting ALK and ROS1 in non-small cell lung cancer patients, which inhibited also the ABL1 kinase in cell-free systems, for the treatment of advanced and therapy-resistant Ph+ leukemia." (PMID 34110462, 2021). "Given the approval of crizotinib to treat late-stage non-small cell lung cancers that are ROS1 positive, this may represent a potential treatment option should this patient experience disease recurrence." (PMID 31995621, 2020). "ROS1 is now recognized as a distinct molecular target in non-small cell lung cancer." (PMID 32308563, 2020).
non-small cell lung carcinoma (continued). "Genomic sequencing of tumor DNA has changed the therapeutic landscape for non squamous, non small cell lung cancer (NSCLC) with the discovery of recurrent oncogenic driver mutations in EGFR, ALK, and ROS‐1 that can be specifically and effectively targeted by new drugs." (PMID 30773851, 2019). "In conclusion, advanced non-small-cell lung cancer in patients with ROS1 rearrangements, treated with crizotinib, may be accompanied by fatal ILD in the initial period." (PMID 30029601, 2018). "ROS1 rearrangement is observed in 1–2% of non-small cell lung cancers (NSCLC)." (PMID 28717217, 2017). "Rearrangements of the ROS1 gene occur in 1–2 % of non-small cell lung cancers (NSCLCs)." (PMID 27535289, 2016). "Defining distinctive histologic characteristics of ROS1-rearranged non-small-cell lung carcinomas (NSCLCs) may help identify cases that merit molecular testing." (PMID 27708233, 2016). "The screening of ROS proto-oncogene 1, receptor tyrosine kinase(ROS1) fusion rearrangement might be potentially beneficial for an effective therapy against non-small cell lung cancer (NSCLC)." (PMID 27488371, 2016). "Other sequence-based tests have been launched commercially that target common, potentially druggable oncogene fusions in ALK, RET, and ROS1 in non-small cell lung cancer (NSCLC), a test historically carried out by immunohistochemical assays such as fluorescence in situ hybridization." (PMID 27784341, 2016). "ROS1 rearrangement is a novel molecular subgroup of non-small-cell lung cancer (NSCLC)." (PMID 27738334, 2016). "Since foretinib appears as a more potent inhibitor than crizotinib also in patients with ROS1-rearranged non-small-cell lung carcinoma, further in vivo studies revealed anti-tumorigenic effects of foretinib in lung metastasis and in patients with sonic hedgehog-driven medulloblastoma." (PMID 26436697, 2015). "For example, the National Comprehensive Cancer Network (NCCN) guidelines for non-small cell lung cancer (NSCLC) recommend measurement of genomic alterations in seven different genes (EGFR, ALK, ERBB2 (encodes HER2 protein), BRAF, MET, ROS1 and RET) to guide twelve different matched therapies." (PMID 26474073, 2015). "Of note, a recent paper has revealed that 9 % of the 65 evaluated BTC cases showed ROS1 rearrangements at genetic analysis: as in non-small cell lung cancer, this may pave the way for the clinical evaluation of specific inhibitors in aBTC patients." (PMID 26693938, 2015). "A number of molecular aberrations have been identified in non small cell lung cancer (NSCLC), including EGFR, BRAF, HER2 mutations, EML4-ALK, ROS1 and RET rearrangements in adenocarcinoma; FGFR mutations/amplifications, DDR2 or PIK3CA mutations in squamous cell carcinoma." (PMID 24898067, 2014). "Similarly, entrectinib and repotrectinib, which also inhibit Receptor tyrosine kinase 1 ROS1, are approved for ROS1-mutated non-small cell lung cancer; however, it is not approved under tumor-agnostic indications." (PMID 40183077, 2025). "For example, the systemic treatment of advanced non-small cell lung cancer remained conventional chemotherapy for several decades until the emergence of TKI therapy following the discovery of several driver mutations including EGFR, ALK, ROS1, MET, RET, BRAF, and ERBB2/HER2." (PMID 39409947, 2024). "Non-small cell lung carcinoma (NSCLC) therapy has been transformed by the identification of actionable oncogenic driver mutations, of which ALK, ROS1, RET fusions and MET exon 14 skipping represent interesting drug targets." (PMID 38492039, 2024). "The College of American Pathologists and the Association of Molecular Pathology guidelines recommend EGFR, ALK and ROS1 gene tests as mandatory in non-small cell lung carcinoma(NSCLC)." (PMID 35446881, 2022).